PPP1R27 (protein phosphatase 1 regulatory subunit 27)
Description:
Inhibits phosphatase activity of protein phosphatase 1 (PP1) complexes.
Synonyms: DYSFIP1; toonin
Tractability: Antibody: the Human Protein Atlas places it where antibodies can reach. PROTAC: ubiquitination databases record sites on it.
Gene: Protein-coding gene on chromosome 17 (81,833,488 to 81,835,050, reverse strand). Ensembl gene ENSG00000182676.
Subcellular location (Human Protein Atlas): Cytosol; Plasma membrane
Gene Ontology:
Molecular function: phosphatase binding; protein binding
Genetic constraint (gnomAD): Loss-of-function variants: 13 observed, 12.56 expected, observed/expected ratio (o/e) 1.04, 90% interval 0.67 to 1.62. The upper end of that interval is the gene's LOEUF score, 1.62, which puts it in group 6 of 6, group 1 being the genes least tolerant of losing a copy. Missense variants: 246 observed, 214.14 expected, observed/expected ratio (o/e) 1.15, 90% interval 1.03 to 1.28. Synonymous variants: 98 observed, 85.87 expected, observed/expected ratio (o/e) 1.14, 90% interval 0.97 to 1.35.
Homologues: Orthologues: chimpanzee PPP1R27 (100% identical), macaque PPP1R27 (96% identical), mouse Ppp1r27 (95% identical), rat Ppp1r27 (94% identical), dog PPP1R27 (94% identical), pig PPP1R27 (91% identical), guinea pig PPP1R27 (90% identical), tropical clawed frog ppp1r27 (67% identical), zebrafish ppp1r27a (61% identical), zebrafish ppp1r27b (60% identical). Paralogues in human: PPP1R12C (40% identical), PPP1R12A (37% identical), PPP1R12B (37% identical).
Diseases named in the same sentence as PPP1R27 in open-access papers:
PPP1R27 is named in the same sentence as 3 diseases in open-access papers, as found by Europe PMC text mining. Sharing a sentence is not in itself a finding about the gene and the disease. The quoted sentences say what the papers report.
epilepsy (1 paper, 2014). A brain disorder characterized by episodes of abnormally increased neuronal discharge resulting in transient episodes of sensory or motor neurological dysfunction, or psychic dysfunction. "Similar consideration of the low tolerance genes suggests that just one, PPP1R27, is likely to harbor a mutation that promotes epilepsy." (PMID 24795746, 2014).
cancer (1 paper, 2022). A tumor composed of atypical neoplastic, often pleomorphic cells that invade other tissues. "Nonetheless, there is little information regarding the biological functions of PPP1R27 and TIGD3 in cancer." (PMID 35676660, 2022).
tumor (1 paper, 2022). "Using data from the HPA database, we found immunohistochemical images of five prognostic signature genes in normal and tumor tissues, including three upregulated genes (ANKLE1, PPP1R27, and AMH) and two downregulated genes (FLRT3 and PPBP)." (PMID 35676660, 2022).